CBLB (Cbl proto-oncogene B)
Diseases named in the same sentence as CBLB in open-access papers (continued):
Sharing a sentence is not in itself a finding about the gene and the disease.
diabetes (4 papers, 2018 to 2022). "This is reflected by the increased induction of chemokine transcripts by plasma of siblings with low HLA risk and individuals with diabetes, and elevated induction of regulatory transcripts (IL2RA, CBLB, SMURF1, SMURF2, SKI) by plasma of siblings with high HLA risk and unrelated control individuals." (PMID 30167736, 2018). "The current study also found that circ-CBLB expression was significantly upregulated in GDM patients, which has not been previously reported in diabetes." (PMID 35046894, 2021).
homocystinuria (4 papers, 2018 to 2025). An autosomal recessive inherited metabolic disorder caused by mutations in the CBS, MTHFR, MTR, and MTRR genes. "The mut, cblA, cblB, and cblH types show only MMA and are therefore called isolated MMA; cblC, cblD, and cblF deficiencies are usually associated with homocystinuria, and the resulting condition is called combined methylmalonic aciduria and homocystinuria (MMA-HC)." (PMID 36777632, 2023).
Insulin resistance (4 papers, 2017 to 2022). Increased resistance towards insulin, that is, diminished effectiveness of insulin in reducing blood glucose levels. "Further functional studies showed that the loss of specificity of CBLB led to insulin and glucose tolerance test response disorder, and blocking CBLB-induced macrophage activation could improve insulin resistance." (PMID 35046894, 2021).
lung adenocarcinoma (4 papers, 2020 to 2024). A carcinoma that arises from the lung and is characterized by the presence of malignant glandular epithelial cells. "Analysis of the Cancer Genome Atlas Program expression data revealed a significant correlation between high CBLB expression and reduced survival in lung squamous cell carcinoma, with a similar yet nonsignificant trend observed also in lung adenocarcinoma." (PMID 39475596, 2024).
metastatic tumors (4 papers, 2014 to 2026). "The deletion or inactivation of CBLB could make natural killer cells spontaneously resist metastatic tumors." (PMID 33195489, 2020).
systemic candidiasis (4 papers, 2017 to 2023). "Moreover, E3 ubiquitin ligase CBLB protein negatively regulates macrophage and dendritic cell anti-Candida functions with Cblb−/− mice more resistant to Candida infection." (PMID 28217127, 2017). "Thus, targeting CBLB and FcεRII may have therapeutic implications for systemic candidiasis." (PMID 34964702, 2022). "Specifically, the E3-ubiquitin ligase CBLB targets DECTIN-1, DECTIN-2, and SYK for ubiquitination and degradation in macrophages (and DCs) and leads to impaired inflammasome activation, oxidative burst, and fungal killing and increased mortality during systemic candidiasis." (PMID 34964702, 2022).
Arthritis (3 papers, 2012 to 2020). Inflammation of a joint. "One of the three significant SNPs from BTA1 is located 285,955 bp upstream of CBLB gene, known to cause arthritis in rats." (PMID 33281874, 2020).
glioma (3 papers, 2017 to 2025). A benign or malignant brain and spinal cord tumor that arises from glial cells (astrocytes, oligodendrocytes, ependymal cells). "Taken together, these results suggest that miR-3591-3p can directly target CBLB, induce M2 macrophage polarization, and promote glioma progression." (PMID 36085418, 2022). "To explore the relationship of CBLB with the immune response and immune microenvironment, we quantified tumor-infiltrating immune cells in glioma tissues from transcriptomic data by single-sample gene set enrichment analysis (ssGSEA)." (PMID 36085418, 2022). "Moreover, overexpression of CBLB reversed the promotive effect of miR-3591-3p-overexpressing macrophages on glioma cell invasion and migration." (PMID 36085418, 2022). "Glioma-released exosomal miR-3591-3p promotes macrophage to the M2 phenotype by targeting CBLB to activate the JAK2/PI3K/Akt/mTOR and STAT3, thereby promoting glioma progression." (PMID 40443670, 2025). "In summary, we found that exosomal miR-3591-3p can facilitate macrophage polarization toward the M2 phenotype by targeting CBLB to activate the JAK2/PI3K/Akt/mTOR and STAT3 pathways, which in turn promotes glioma progression." (PMID 36085418, 2022). "Mechanistically, miR-3591-3p can directly target CBLB and MAPK1 in macrophages and glioma cells, respectively, and further activate the JAK2/PI3K/AKT/mTOR, JAK2/STAT3, and MAPK signaling pathways." (PMID 36085418, 2022).
muscle atrophy (3 papers, 2021 to 2025). The loss of muscle tissue due to inactivity or disease. "Previous reports suggest the role of CBLB gene in skeletal muscle atrophy in mice by negative regulation of growth factors during cell differentiation and development." (PMID 34785720, 2021).
myocardial infarction (3 papers, 2024). Gross necrosis of the myocardium, as a result of interruption of the blood supply to the area, as in coronary thrombosis. "Our findings suggest that overexpression of CBLB significantly lessens myocardial infarction in AMI mice, modifies gut microbial abundance, and influences the expression of certain metabolites and genes." (PMID 39004726, 2024). "Our initial observations reveal that overexpression of CBLB significantly curtailed the degree of myocardial infarction in AMI mice, which is consistent with our hypothesis." (PMID 39004726, 2024). "The expressions of CBLB and ZNF302 in serum collected at 48 h and 1 week post-myocardial infarction were significantly higher compared to the sham operation group." (PMID 38827298, 2024). "The serum of mice was collected at three different time points for analysis, revealing an increase in the expression of CBLB and ZNF302 at 3 h post-myocardial infarction." (PMID 38827298, 2024). "Moreover, our data indicated that CBLB intervention markedly reduced the proliferation of collagen fibers, suggesting potential preventive and therapeutic roles of CBLB in myocardial fibrosis, a prevalent complication post-myocardial infarction impacting heart’s systolic and diastolic functions." (PMID 39004726, 2024).
breast tumor (2 papers, 2018 to 2019). "In breast tumors, the mechanism can be reversed by miR-27b, which down-regulates Casitas B-lineage lymphoma proto-oncogene-b (CBLB) and GRB2 genes, two up-stream controllers of ERK." (PMID 31117237, 2019). "Notably, expression of the CD81 interactor and HCV entry facilitator CBLB is altered in gastric and breast tumor tissue and CBLB regulates cell migration and epidermal to mesenchymal transition (EMT) through EGFR degradation." (PMID 30024968, 2018).
endotoxemia (2 papers, 2023 to 2025). "It has been reported that CBLB combined and ubiquitinates the inflammasome NLRP3, leading to its proteasome degradation and migrating endotoxemia." (PMID 38105184, 2023).
hepatoma (2 papers, 2018 to 2023). "Moreover, CAPN5 and CBLB appear to be strongly associated with the CD81 complex as their total abundance in human hepatoma cell lysates was comparably low as quantified by intensity based absolute quantification (iBAQ)." (PMID 30024968, 2018). "Knockout of CD81 almost completely abrogated susceptibility of human hepatoma cells to HCV.Taken together we find that the CD81 interaction partners CAPN5 and CBLB are HCV host dependency factors." (PMID 30024968, 2018). "While we discovered CAPN5 as CD81 interaction partner in hepatoma cells and primary human hepatocytes, we included CBLB as a hit from the STRING network analysis." (PMID 30024968, 2018). "A proteomic analysis mapped 33 host protein interactions of CD81 in primary human liver and hepatoma cells, including for example protein CAPN5 (calpain-5) and ubiquitin ligase CBLB (Casitas B-lineage lymphoma proto-oncogene B), capable of forming a complex with CD81 and implicated in HCV entry." (PMID 37046846, 2023). "CAPN5 and CBLB were dispensable for CoV and VSV infection in human hepatoma cells." (PMID 30024968, 2018). "Neither CAPN5 nor CBLB affected surface expression of SCARB1, CD81, CLDN1 and OLCN on human hepatoma cells." (PMID 30024968, 2018). "In line with this, we demonstrate that CAPN5 and CBLB promote HCV entry, but not Plasmodium entry into human hepatoma cells." (PMID 30024968, 2018).
rheumatoid arthritis (2 papers, 2025). A chronic, systemic autoimmune disorder characterized by inflammation in the synovial membranes and articular surfaces. "Clinical data reveal low expression levels of circ-CBLB in rheumatoid arthritis patients, correlating negatively with immunoinflammatory indices." (PMID 40746530, 2025). "We found that circ-CBLB expression was significantly reduced in the synoviocytes of rheumatoid arthritis patients (p<0.01), and similarly in exosomes (p<0.01)." (PMID 40746530, 2025). "In conclusion, circ-CBLB promotes macrophage polarization toward the M1 phenotype by regulating the TLR3/TRAF3 signaling pathway, thereby exacerbating the inflammatory response in rheumatoid arthritis." (PMID 40746530, 2025).
brain cancer (1 paper, 2024). A primary or metastatic malignant neoplasm affecting the brain. "Likewise, some siRNA-based therapies have been proposed, including the use of an inhibitor of Cbl proto-oncogene B (CBLB), which is being investigated in several cancers, including brain cancer, and it is currently in phase I." (PMID 38473710, 2024).
chronic myeloid leukemia (1 paper, 2024). "Recent published studies showed that Axl was identified as ubiquitylation substrates for E3-ligase CBLB in chronic myeloid leukemia." (PMID 39423241, 2024). "CBLB can regulate Axl protein stability in chronic myeloid leukemia and NK cells." (PMID 39423241, 2024).
cognitive deficits (1 paper, 2024). "This could be linked to the cognitive deficits observed in schizophrenia patients, wheredownregulation of CBLB might impair memory and synaptic function." (PMID 40162448, 2024). "Conversely, CBLB downregulation may disruptproteasome-mediated protein degradation, immune regulation and the EGF pathway, potentially leading to cognitive deficits and synapticdysfunction." (PMID 40162448, 2024).
mastitis (1 paper, 2020). Inflammation of breast tissue during lactation or postpartum due to an obstructed duct or infection. "Taken together, bta-miR-223 is a predominant miRNA involved in mastitis, and bta-miR-223 likely mitigates the inflammatory progression by targeting CBLB and inhibiting the downstream PI3K/AKT/NF-κB pathway." (PMID 33195489, 2020). "Therefore, our findings strongly suggest that CBLB promotes the inflammatory damage in mastitis via the PI3K/AKT/NF-κB pathway." (PMID 33195489, 2020). "In addition, bta-miR-223 likely down-regulated the inflammatory response in the LTA-stimulated Mac-T cells by targeting CBLB, indicating that it is involved in the host immune response against S. aureus-induced mastitis." (PMID 33195489, 2020).
myeloma (1 paper, 2023). "They showed that CBLB knockout PNK cells have higher cytotoxicity against the myeloma cell lines RPMI8226 and U266 and the plasma cell leukemia cell line ARH77." (PMID 38003255, 2023).
papilloma (1 paper, 2023). A benign epithelial neoplasm that projects above the surrounding epithelial surface and consists of villous or arborescent outgrowths of fibrovascular stroma. "We also investigated the protein expression level of these mutations, the results showed four proteins (HRAS, ALDH7A1, CBLB, and MPRIP) were differently expressed between papilloma and PUC." (PMID 37704624, 2023).
preeclampsia (1 paper, 2025). Preeclampsia is a hypertensive disorder of pregnancy that is characterized by new-onset hypertension with proteinuria presenting after 20 weeks of gestation, and depending on mild or severe forms may initially present with severe headache, visual disturbances, and hyperreflexia. "Lastly, we found that the SLC9A9, SH2B3, SDC3, RCC2, F13A1, CCL2, and CBLB in macrophages were likely to be correlated with preeclampsia." (PMID 40216654, 2025). "Of all the immune cell-regulated preeclampsia differential genes SLC9A9, SH2B3, SDC3, RCC2, F13A1, CCL2, and CBLB were consistently expressed in two transcriptome datasets, and all were highly expressed in macrophages." (PMID 40216654, 2025).
sarcopenia (1 paper, 2026). Progressive decline in muscle mass due to aging which results in decreased functional capacity of muscles. "By using ML algorithms and expression analysis techniques, this study further validated several URGs including CBLB, PSMD6, RNF115, SMAD3, UCHL3 and ZBTB16 as potential markers associated with sarcopenia." (PMID 41560007, 2026).
schizophrenia (1 paper, 2024). A major psychotic disorder characterized by abnormalities in the perception or expression of reality. "The downregulation of CBLB, which encodes an E3 ubiquitin-protein ligase, suggests disruptions in proteasome-mediated proteindegradation and immune regulation in schizophrenia." (PMID 40162448, 2024). "The highlight of this study was the identification of four key genes associated with schizophrenia: significant upregulation ofS100A8, S100A9 and BCL2A1 and downregulation of CBLB." (PMID 40162448, 2024). "Additionally, one gene, CBLB, was significantly downregulated in schizophrenia patients and was common toboth the discovery and validation datasets." (PMID 40162448, 2024). "The involvement of CBLB in the EGF (Epidermal Growth Factor) pathway points to itspotential role in dopaminergic and GABAergic neuron development, which are critical in schizophrenia's neuropathology." (PMID 40162448, 2024). "This study identified key molecular changes in schizophrenia, notably the upregulation of S100A8, S100A9 and BCL2A1 and thedownregulation of CBLB, highlighting the involvement of neuro-inflammatory pathways, apoptosis regulation and immune modulation in thedisease." (PMID 40162448, 2024).
scrub typhus (1 paper, 2011). Scrub typhus is a rare dust mite-borne infectious disease caused by the Orientia tsutsugamushi bacterium and characterized clinically by an eruptive fever which is potentially serious. "The transcriptional signature of patients with scrub typhus included the differential expression of the CBLB, LOC642161, CD8A, CD8B1 and FOSB genes, when compared to healthy controls and patients with other infectious diseases." (PMID 21610853, 2011).
tumor (69 papers, 2012 to 2025). "Moreover, in the case of the CBLB gene, 13 mutations were identified in TCGA ductal luminal samples associated with overexpression of their host gene and repression of tumor suppressive activity of TGF-β pathway." (PMID 32365829, 2020). "CBLB-deficient mutations mice could develop a certain degree of spontaneous malignant tumor resistance, could spontaneously reject tumor cells which expressing human papilloma virus Ags, showed a high survival rate during fatal systemic infection." (PMID 33195489, 2020). "CBLB‐deficient T cells have increased anti‐tumor efficacy, suggesting that CBLB might be exploited as a drug target for the purpose of boosting T‐cell responses against tumors." (PMID 27474268, 2016). "In our study, we observed that CBLB expression was widespread in multiple effector immune cell subtypes, with a notable increase in the most tumor-reactive immune cell types following nivolumab treatment." (PMID 39475596, 2024). "We found that knockdown of CBLB enhanced the proliferation and migration of tumor cells, while overexpression had the opposite effect." (PMID 38105184, 2023). "Whereas, the results of subcutaneous tumor formation in mice also revealed that the expression of CBLB was negatively correlated with tumor proliferation." (PMID 38105184, 2023). "A study has found that exosomes can activate the JAK2/PI3K/Akt pathway by targeting CBLB, promote macrophage polarization to the M2 phenotype, and subsequently promote tumor progression." (PMID 37781198, 2023). "In the case of the CBLB gene, several mutations were identified in TCGA IDC-LM-BRCA samples associated with overexpression of this gene and repression of tumor suppressive activity of TGF-β pathway." (PMID 32365829, 2020). "Our data are therefore consistent with a role of miR‐27a as tumour suppressor and that its downregulation leads to an upregulation of the pro‐oncogenic CBLB and CCNG1." (PMID 32133790, 2020). "Similarly, the C4 subgroup was identified in the tumor tissues of the validation cohort, exhibiting a high similarity to CD4_THEMIS cells and expressing high levels of CBLB, THEMIS, and CAMK4." (PMID 38948071, 2024). "In addition, we also transfected inhibitor into CBLB knockdown tumor cells, and the results of WB analysis and immunoprecipitation also suggested the same results." (PMID 38105184, 2023). "The results demonstrated that overexpression of CBLB could reverse the promotion of mimics on the proliferation and migration of tumor cells." (PMID 38105184, 2023). "CBLB is a proto-oncogene considered as a new target for tumor immunotherapy." (PMID 38105184, 2023). "Furthermore, the results of the Tumor Immune Estimation Resource (TIMER) database analysis confirmed that the infiltrating levels of M2-type macrophages were negatively correlated with CBLB expression in both GBM and Lower-grade glioma (LGG)." (PMID 36085418, 2022). "Notably, RGS1, CBLB, and FYN were expressed at higher levels, while IFNG was expressed at lower levels across all tumor-infiltrating NK clusters compared to the preinfusion NK clusters." (PMID 40315330, 2025). "Tumor-infiltrating PDCD1+ and LAG3+ cells expressed CBLB, while a minor proportion expressed CBLC." (PMID 39030301, 2024). "CBLB was brought up among more than 100 ubiquitin-related target genes in lymphoid infiltration, and it was found to be among the top E3 ubiquitin ligases co-expressed with PDCD1 and LAG3 in the tumor microenvironment (Dataset EV3)." (PMID 39030301, 2024). "WB analysis results showed CBLB was highly expressed in the non-cancerous tissue of colon but lower in the tumor tissues." (PMID 38105184, 2023). "As these kinases are proto-oncoproteins, CBLC may serve a tumor suppressive function similar to its close homologs, CBL and CBLB." (PMID 38045004, 2023).
cancer (54 papers, 2012 to 2025). A tumor composed of atypical neoplastic, often pleomorphic cells that invade other tissues. "Our report highlights the importance of considering the increased risk of cancer in long-term follow-up of MMA cblB patients, especially after solid organ transplantation." (PMID 38444575, 2024). "Given the most recent literature, the circulating MKC seems to have been rediscovered for cancer-associated cbLB, yet often by accident and sometimes failing to investigate their actual nature." (PMID 32218149, 2020). "And CBLB also regulates Axl protein stability expressed in natural killer cells to participate in cancer metastasis." (PMID 39423241, 2024). "MG was associated with SNPs in hallmarks of cancer–related genes such as the microtubule-associated tumor suppressor MTUS1, leukocyte-associated gene LAIR2, and Cal proto-oncogene CBLB." (PMID 35711735, 2022). "This cell type has been exhaustively described for cancer cbLB and reviewed with respect to phenotyping, isolation, and clinical use." (PMID 32218149, 2020). "In this regard, siRNA-mediated knockdown of CBLB is currently being investigated as a therapeutic approach to enhance antitumor responses in cancer patients." (PMID 28184224, 2017). "In conclusion, the mature EnC has been proven useful in cancer cbLB with regard to quantification." (PMID 32218149, 2020). "For cbLB in particular cancer cbLB, the epithelial progenitor cells remain largely uninvestigated." (PMID 32218149, 2020). "Furthermore, studies have confirmed that CBLB knockout or deletion can promote the immune activation of CD8 + T cells and enhance the cytotoxicity of NK cells in cancer immunotherapy." (PMID 38105184, 2023).